ADAM9 (ADAM metallopeptidase domain 9)
Diseases named in the same sentence as ADAM9 in open-access papers (continued):
Sharing a sentence is not in itself a finding about the gene and the disease.
tumor (continued). "Additionally, α6β1 on platelets binds to ADAM9 on tumor cells, facilitating platelet activation and tumor cell extravasation." (PMID 37046617, 2023). "αIIbβ3 may participate in platelet–tumor cell interaction in tumor metastasis through the binding of metalloproteinase domain-containing protein 9 (ADAM-9)." (PMID 36975471, 2023). "This evidence supports the important impact of ADAM9 upon tumor progression." (PMID 36778124, 2023). "Furthermore, ADAM9 showed significantly different expression between tumour and para-carcinoma tissues in KIRC using qRT-PCR analysis." (PMID 37082201, 2023). "Next, we addressed whether ADAM9 blockade enhances the therapeutic efficacy of PCa in tumor xenograft mouse models." (PMID 36778124, 2023). "Owing to its role as a stress-induced transcriptional repressor of plasminogen activator inhibitor-1 expression, ADAM9 may promote tumor vascularization." (PMID 36572816, 2023). "Similarly, the level of ADAM9 expression is correlated with tumor size, local tumor invasion, the presence of lymph node metastases and TNM staging." (PMID 37185715, 2023). "The authors suggest that ADAM9 influences tumour cells via two possible ways—interaction with adhesion molecules, or the proteolytic ‘shedding’ of signalling molecules, which leads to the activation of their receptors, including the EGF receptor and its ligands." (PMID 35565436, 2022). "ADAM9 is known to be involved in tumor formation and progression, especially in HNSCC." (PMID 36553675, 2022). "ADAM9 influences the inflammation, developmental process, degenerative diseases and tumor biology." (PMID 33811456, 2022). "These conclusions verified our hypothesis that ADAM9 could promote tumor cell metastasis through elevated cell migration and degrading collagens." (PMID 36434634, 2022). "Moreover, increasing evidence has shown that ADAM9 plays an important role in the invasion and migration of tumor cells." (PMID 33811456, 2022). "However, the ablation of ADAM-9 reduced the proliferation and tumor growth and increased the differentiation, decreasing the metastatic ability while increasing the sensitivity to chemotherapeutic drugs." (PMID 33808504, 2021). "Notably, the tumor size was significantly bigger in the control group than in the ADAM9 knockdown group." (PMID 34671207, 2021). "A limitation to the applicability of our ADAM9-MSNs, and one that in fact pertains to all current treatments, could be limited penetration and accumulation in the tumor due to the dense stroma present in PDAC." (PMID 34282781, 2021). "Furthermore, higher expression levels of ADAM9, EFNB2, MET, and TMOD3 were significantly associated with increased tumor infiltration of macrophages, DCs and/or B cells." (PMID 33648511, 2021). "Furthermore, the expressions of ADAM9 in 30 fresh OC tumor samples and the adjacent normal tissue were compared by RT‐qPCR methods." (PMID 31793719, 2020). "In addition to metastasis, ADAM9 also plays an important role in tumor proliferation, angiogenesis, and even immune evasion." (PMID 33096780, 2020). "Among them, ADAM9 can not only participate in the degradation of extracellular matrix as a metalloprotease, but also mediate tumor cell adhesion through its deintegrin domain, which is closely related to tumor invasion and metastasis." (PMID 32875951, 2020). "This suggests that ADAM9 participates in the chemo-resistance in tumor progression." (PMID 33096780, 2020). "Circ-ADAM9 absorbs and inhibits miR-127, which is a tumor suppressor." (PMID 33096780, 2020). "In addition, after knocking out ADAM9 with siRNA, it was found that the proteolytic activity of the tumor disappeared, supporting ADAM9’s advantages over related proteases." (PMID 32875951, 2020). "ADAM9 participates in the regulation of various tumor processes." (PMID 33096780, 2020). "We were the first to describe ADAM9 overexpression in VS, suggesting it might be a marker for tumor growth and invasiveness." (PMID 33176868, 2020).
tumor (continued). "Recently, increasing evidence has shown that ADAM9 plays an important role in tumor biology." (PMID 33096780, 2020). "Given that tumor cells express both membrane-bound and soluble ADAM9, it is expected that could promote neutrophil activation in the tumor microenvironment." (PMID 33096780, 2020). "Increased ADAM9 expression also correlates with higher tumor grade and progression." (PMID 33096780, 2020). "ADAM9 participates in the regulation of a variety of related tumor processes." (PMID 32875951, 2020). "In addition, ADAM9 was significantly upregulated in primary tumor tissues of HCC (n = 370) compared with adjacent normal liver tissues (n = 50) (t-test p = 4.6 × 10−6)." (PMID 32245188, 2020). "Functional studies focusing on the role of ADAM9 in tumor biology are scarce." (PMID 30556643, 2019). "Taken together, our results emphasize a central role of ADAM9 in mediating tumor angiogenesis." (PMID 30556643, 2019). "High ADAM9 expression correlated with tumor grade and vascular invasion (P < 0.05)." (PMID 30556643, 2019). "We chose to probe the impact of ADAM9 on PDAC tumor cell adhesion to a panel of ECM substrates." (PMID 30556643, 2019). "The subcutaneous tumor growth mimics our clinical data regarding ADAM9 not being associated with tumor size and growth." (PMID 30556643, 2019). "Other metalloproteinases, such as ADAM9, were upregulated after tumor recognition and may play a similar role in downregulating the expression of other NK cell receptors, such as NKG2D or NKp46 and promoting NK cell survival and serial engagement with targets." (PMID 31242243, 2019). "In the murine HGF/CDK4 melanoma model, ADAM9 contributes to tumor formation and metastatic load." (PMID 30556643, 2019). "Notably, smaller tumor growth and lung metastasis in ADAM9 KO TC1 groups compared to control groups were observed in mice bearing lung tumors." (PMID 29118335, 2017). "The results showed that the expression levels of vascular endothelial growth factor A (VEGFA), angiopoietin-2 (ANGPT2), and tissue plasminogen activator (PLAT) were suppressed in ADAM9-silenced cells, which in turn leads to decreases in angiogenesis, vascular remodeling, and tumor growth in vivo." (PMID 29118335, 2017). "It was reported that miR-126 was down-regulated in PC tissues and could act as a tumor suppressor in PC by inhibiting ADAM9, KRAS and CRK which was in accordance with our findings." (PMID 27626307, 2016). "Over-expression of ADAMs (ADAM9, 10, 12, and 17 etc.)is popularly noted in epithelial inflammation and carcinogenesis and increased expression of certain ADAMs may enhance tumor cells invasion, proliferation in vitro and promote tumor formation in vivo." (PMID 26919242, 2016). "ADAM9 is also known to cleave EGF to promote tumour growth and facilitate angiogenesis." (PMID 25980435, 2015). "Since, PC3 cells are known to induce osteolytic lesions in vivo, we determined whether knockdown of ADAM9 expression could attenuate tumor-induced bone resorption." (PMID 23342005, 2013). "ADAM9 and MMP7 are involved in cell-cell and cell-matrix interaction, are able to cleave and release a number of molecules with important role in tumorigenesis, resulting causally involved in tumor formation and progression." (PMID 23437250, 2013). "Recently, it was demonstrated that in vivo gene silencing of ADAM9 reduced tumor metastasis." (PMID 22069567, 2010). "Interestingly also three of the five chromophobe RCC included showed a high ADAM9 expression, although this tumour type is thought to rather originate from the distal nephron." (PMID 18582378, 2008). "Significant associations between the mRNA expression of ADAM9 in RCC and clinico-pathological parameters (tumour stage, grading, nodal status, metastasis, histologic type and residual tumour status) could not be demonstrated (all p > 0.05)." (PMID 18582378, 2008).
tumor (continued). "Whether the demonstrated prognostic value of ADAM9 is independent from other tumour parameters will have to be verified in larger study cohorts." (PMID 18582378, 2008). "As the apical membrane labelling, observed in the adjacent normal pancreatic tissue, is preserved in almost all PDACs, we might speculate that ADAM9 function could at least partly be maintained in the tumour cells." (PMID 14997207, 2004). "If this proved true, ADAM9 might play a role in tumour progression, and might be used not only for prognostic and diagnostic purposes but also for novel therapeutic approaches." (PMID 14997207, 2004). "Upregulated genes were primarily associated with cell adhesion/invasion/metastasis (ELMO2, ADAM9, DLG1, TRPM7), metabolism/mitochondrial function (FAM120A, DARS2), and cellular transport/axonal trafficking (KIF1B, TBC1D5), indicating the presence of tumor microenvironment stress." (PMID 41404060, 2025). "Furthermore, we observed that carriers of the rs6474526 G allele were significantly associated with larger tumors and distal metastases, suggesting that the rs6474526 SNPs in ADAM9 may promote tumor progression by upregulating ADAM9 expression." (PMID 40429751, 2025). "To functionally confirm that our ADAM9-responsive MSNs could indeed be employed across tumor types, we assessed ADAM9-substrate cleavage using conditioned medium collected from different gastrointestinal cancer cell lines (i.e., bladder, colon, duodenum, and esophageal)." (PMID 34282781, 2021). "Mechanistically, nuclear ADAM9, triggered by hypoxia-induced translocation, functions as a transcriptional repressor by binding to promoters of genes involved in the negative regulation of angiogenesis, and thereby promotes tumor angiogenesis in plasminogen/plasmin pathway." (PMID 34671207, 2021). "Metalloproteinases of the ADAM-family digest proteins of the ECM, allowing tumor cells to detach from the tissue and thereby promoting their migration and invasion Thus, highest ADAM9 expression could be detected in areas of liver metastases with high invasive growth." (PMID 33176868, 2020). "Thus the inter-cellular interactions of AXL, FN14, and ADAM9 may be important in regulation of coupling between tumor and stromal cells." (PMID 22570691, 2012). "Additionally performed Kruskal-Wallis tests further confirmed the non-significant associations of ADAM9 expression with M-status (p = 0.096), nodal status (p = 0.098), whereas residual tumour status was of borderline significance (p = 0.050)." (PMID 18582378, 2008). "Elevated ADAM8, ADAM9, ADAM12 and ADAM17 levels were observed in CRC tissues and correlated with more advanced tumor stage, while increased serum ADAM15 concentrations associated with the presence distant metastases." (PMID 41976350, 2026). "An efferocytosis-based prognostic model, EFFscore, developed based on ADAM9, P2RY6, and CD36, can effectively assess the tumor phenotype of PDAC patients." (PMID 41383622, 2025). "Published data show that several ADAMs, including ADAM8, ADAM9, ADAM10, ADAM12, and ADAM17, are overexpressed in tumours." (PMID 40427200, 2025). "In summary, ours is the first study to explore distinct allelic effects of ADAM9 SNPs (rs7006414 and rs6474526) in a Taiwanese population, highlighting their impacts on the incidence of BCR and tumor growth in PCa." (PMID 39628685, 2024). "The mean IRS of ADAM9 and of t-PA were also significantly greater in OSCC cases with large tumor diameters than in those with small tumor diameters (P = 0.020 and P = 0.002, respectively)." (PMID 39441449, 2024). "Its targets have been reported to be IL-8, COL1A1, ADAM9, HMGB1, and SLC2A3, and inducing mir-129-5p overexpression in tumor cells reduced malignant characteristics, including cell proliferation, migration, and invasion." (PMID 39797181, 2024).
tumor (continued). "The results by Spearman correlation test showed that overexpression of ADAM9, CDCP1, or t-PA in OSCC was positively correlated with distinct degrees of tumor cell differentiation, as defined by different histopathological diagnoses." (PMID 39441449, 2024). "It was also indicated that silencing ADAM9 expression in MDA-MB-231 cell lines and subsequently production of ADAM9 knockdown clones of these BC cell lines suppressed the invasion of tumor cells." (PMID 38317965, 2024). "In conclusion, this study demonstrated overexpression of ADAM9, CDCP1, and t-PA in OSCC, which were positively correlated with tumor cell differentiation of OSCC." (PMID 39441449, 2024). "The most-known is the ADAM9/miR-126 axis, which was described in ESCC, GC, HCC and PC, and can function as a tumor- and-metastasis suppressing pathway." (PMID 37185715, 2023). "In single-cell sequencing analysis, ITGA2, ITGA3, ADAM9, and BHLHE40 were all highly expressed in malignant ductal cells, suggesting important roles in tumor progression." (PMID 37377917, 2023). "The ADAM9 relevance in the invasive phenotype of GSCs was evaluated in histological samples of GBM patients and orthotopic xenograft models, reporting an elevated co-expression of ADAM9 and TNC in the invasive front of the tumor tissue." (PMID 37108208, 2023). "In terms of substrates for ADAM9, MICA has substantial functions in tumor immunology, especially targeted by NK cells." (PMID 36572816, 2023). "Different vital tumor-related genes, such as PTEN, VEGF, MMP2, Oct4, and ADAM9, were defined as miR-20b targets." (PMID 36717861, 2023). "In the U251‐shUSP39‐bearing tumor, the expression levels of USP39 and ADAM9 were downregulated compared with that in the U251‐shNC‐bearing tumor." (PMID 33811456, 2022). "Our results provide a mechanistic connection between ADAM9, which is highly expressed in CRC samples, and these tumor-related pathways." (PMID 35780836, 2022). "In PDAC, a significant contribution of ADAM proteases to tumor progression was reported for ADAM8, ADAM9, ADAM10, ADAM12, and ADAM17." (PMID 33578644, 2021). "In agreement with previous reports, we observed that expression levels of ADAM9, ADAM10, ADAM12 and ADAM17 were increased in tumor versus adjacent non tumor tissues except for ADAM10 that was non-significant, all were associated with poor prognosis." (PMID 33805340, 2021). "First, to explore the roles of ADAM9 in OC, the expressions of ADAM9 in the FFPE OC tumor samples and the adjacent non‐tumorous tissues were compared by IHC methods." (PMID 31793719, 2020). "Taken together, these results identify an important molecule ADAM9 in regulating BTIC invasiveness and maintaining tumor cell regeneration." (PMID 32875951, 2020). "Several studies have shown that miR-126 targets include ADAM9, LRP6, PIK3R2, CXCR4, and SLC7A5, all of which participate in the development of diverse tumor types." (PMID 32554852, 2020). "Similar to other miRNAs in various tumor types, the binding sites are located in the 3′-UTR of ADAM9." (PMID 33096780, 2020). "As an initial step to investigate the involvement of ADAM9 in PDAC tumor biology, we investigated its expression in a cohort of >100 clinically annotated tumor samples by IHC analysis of a tissue microarray." (PMID 30556643, 2019). "Our study highlights that ADAM9 plays an important role in PDAC tumor biology, affecting tumor angiogenesis, cell migration, adhesion to different ECM substrates, and anchorage‐independent growth." (PMID 30556643, 2019). "Next, we transplanted ADAM9 WT and KO TC1 cells into mice by subcutaneous injection and monitored the subsequent tumor growth." (PMID 29118335, 2017). "Of note, tumor-induced MDSC are enriched for multiple ecto-proteases including ADAM28, ADAM9, collagenase-3 (MMP13), stromelysin (MMP3), macrophage elastase, and leukocyte elastase." (PMID 27929373, 2016).
tumor (continued). "Furthermore, our investigation revealed a notable upregulation of several matrix metalloproteinases (MMPs) in tumor-infiltrating macrophages, including MMP9, MMP12, MMP19, ADAM8, ADAM9, and ADAM17." (PMID 38254761, 2024). "Our findings suggest that the rs7006414 promoter SNP and the rs6474526 intronic SNP may influence ADAM9 gene expression, thereby contributing to promoting BCR and tumor growth in PCa." (PMID 39628685, 2024). "In vitro and in vivo studies have demonstrated the role of ADAM9 in the progression of pancreatic cancer by directing such processes such as angiogenesis, cell migration, matrix adhesion extracellular or tumor growth independent of anchors." (PMID 37185715, 2023). "WNT4 had decreased expression (logFC = −1.6), and the expression of seven mRNAs (CDK4, MAPK1, TGFB, ZEB2, AURKA, SOX4, and ADAM9) in tumor samples was not notably different from that in the group of normal tissues." (PMID 35453574, 2022). "ADAM9 was shown to degrade ECM proteins, indicating its metastatic potential in tumor progression." (PMID 36358879, 2022). "ADAM9 mRNA was significantly upregulated in CRC tissues as compared with adjacent nontumorous tissues taken from the same patients, suggesting a role for this protease in CRC carcinogenesis and/or tumor progression." (PMID 35780836, 2022). "Furthermore, for assessing the ADAM9 role in HCC cell tumorigenicity after irradiation, subcutaneous tumor formation experiments in nude mice were conducted." (PMID 34528498, 2021). "Furthermore, there are a number of ADAM proteases lacking phenotypes in knockout mice but with a possible role in different tumor entities and specifically in PDAC, which applies for ADAM8 and ADAM9." (PMID 33578644, 2021). "Several proteins were aberrantly regulated, and among these were ECM proteins and other enzymes altered at the tumor-stroma border in the absence of host-derived ADAM9." (PMID 32906814, 2020). "We observed abundant staining of ADAM9 in tumor tissues from TNBC patients compared with tumor tissues from non-TNBC patients." (PMID 32637415, 2020). "In this in vivo setting, ADAM9 was also found to foster angiogenesis without an impact on tumor cell proliferation." (PMID 30556643, 2019). "ADAM9 expression was predominantly observed in the tumor cells with limited or no expression in the stromal regions." (PMID 30556643, 2019). "Based on these conflicting observations, we postulate that the ADAM9‐dependent difference in tumor volume is not an intrinsic property of the tumor cell but rather depends on the cellular/stromal microenvironment." (PMID 30556643, 2019). "Both ADAM9 and FGFR1 are important factors in tumor development and metastasis induction." (PMID 31409686, 2019). "In addition, we stained for the endothelial marker CD31 to detect angiogenesis in tumor specimens and found lower expression of CD31 in the ADAM9 KO tumors." (PMID 29118335, 2017). "Similarly, MIR126 was found to suppress tumours by directly targeting the insulin receptor substrate-1 (IRS1) and the disintegrin- and metalloproteinase domain-containing protein-9 (ADAM9)." (PMID 27119351, 2016). "Furthermore, relative expression levels of ADAM9 and CDCP1 in tumor compared to normal part were measured among these samples." (PMID 26553452, 2015). "In particular, the genes ADAM9, AXL, and TNFRSF12A may connect directly between mesenchymal tumor cells and stromal cells." (PMID 22570691, 2012). "Similarly, WWP1, SDC1 (syndecan 1), EZH2, CCND1, ADAM9 and MEMO1 have oncogenic activities and are targeted by the potentially tumor suppressor miRNA miR-195, miR-10b, let-7c, miR-17 and miR-125b." (PMID 21375733, 2011). "The Cox multivariate survival analysis revealed no independent prognostic value for ADAM9 expression and tumour grading whereas pT-and pM-stage remained highly significant." (PMID 18582378, 2008).